RNU6-970P (RNA, U6 small nuclear 970, pseudogene)
Gene: Small nuclear RNA gene on chromosome 1 (92,969,604 to 92,969,710, reverse strand). Ensembl gene ENSG00000252121.
Homologues: Orthologues: chimpanzee U6 (97% identical), macaque U6 (92% identical), dog U6 (79% identical), mouse Gm23407 (62% identical). Paralogues in human: RNU6-1145P (88% identical), RNU6-29P (88% identical), RNU6-20P (87% identical), RNU6-38P (87% identical), RNU6-393P (87% identical), RNU6-16P (86% identical), RNU6-25P (86% identical), RNU6-41P (86% identical), RNU6-616P (86% identical), RNU6-1 (85% identical), RNU6-1316P (85% identical), RNU6-1336P (85% identical), and 1284 more.